EIF5A (eukaryotic translation initiation factor 5A)
Diseases named in the same sentence as EIF5A in open-access papers (continued):
Sharing a sentence is not in itself a finding about the gene and the disease.
ovarian carcinoma (11 papers, 2002 to 2022). A malignant neoplasm originating from the surface ovarian epithelium. "EIF5A was found to be dysregulated in high-grade colon and in rectal carcinoma and in several other tumour types, such as glioblastoma, cervical and ovarian cancer, bladder cancer and non-small-cell lung cancer." (PMID 34830804, 2021). "EIF5A2, an isoform of eIF5A and located on chromosome 3q26, was first discovered in ovarian carcinoma and has been identified as a novel oncogene in many human cancer cells." (PMID 30175116, 2018). "To date, two human isoforms of eIF5A have been identified (eIF5A1 and eIF5A2) and amplification of the eIF5A2 gene has been found in ovarian cancer." (PMID 11953842, 2002). "Additionally, eIF-5A and/or eIF-5A2 have been proposed as a transforming and predictive factor in the development of hepatocellular carcinoma, non-small cell lung cancer and in patients with ovarian carcinoma." (PMID 22927971, 2012). "eIF-5A was found to be overexpressed in samples from colorectal adenoma and eIF-5A2 is present in various cancer cell lines and its overexpression may serve as a prognostic marker in patients with urothelial carcinoma or ovarian cancer." (PMID 22927971, 2012). "In summary, eIF5A, an indispensable member of the translation initiation process, is found to be aberrantly expressed in different malignancies including HCC, ovarian cancer, and lung cancer." (PMID 23029619, 2012). "The significant markers eIF5A, eIF2G and eEF1A have not been clearly correlated to clinical parameters of prognostic value in ovarian cancer." (PMID 35718769, 2022).
glioblastoma (10 papers, 2012 to 2024). The most malignant astrocytic tumor (WHO grade IV). "This underscores the role of hypusinated eIF-5A in transformation or propagation of tumor cells, since glioblastomas are possibly derived from progenitors along the neural stem cell-astrocytic axis or de-differentiated astrocytes." (PMID 22927971, 2012). "Taken together, these data establish an important role for eIF-5A and the hypusine synthesizing enzymes in proliferation of glioblastoma cells." (PMID 22927971, 2012). "Treatment of glioblastoma cells with GC7 in vitro resulted in a reduced amount of modified eIF-5A (50% in G55T2 and 45% in U87-MG) indicated by a second, more acidic eIF-5A spot in 2D-Western blot." (PMID 22927971, 2012). "To evaluate the possible role of functional eIF-5A as a potential therapeutic target in glioblastomas, we treated tumor derived cell lines with GC7, a well established specific inhibitor of desoxyhypusine synthase (DHS), and compared its antiproliferative effect to treated primary astrocytes." (PMID 22927971, 2012). "Thus we investigated the potential of eIF-5A and the hypusine forming enzymes as possible novel targets for glioblastoma therapy." (PMID 22927971, 2012). "Here we report that eIF-5A as well as the hypusine-forming enzymes deoxyhypusine synthase (DHS) and deoxyhypusine hydroxylase (DOHH) are highly overexpressed in glioblastoma patient samples." (PMID 22927971, 2012). "We found a general eIF-5A overexpression in tumor cells and an upregulation of DHS and DOHH in glioblastomas compared to tumors of grade I–III." (PMID 22927971, 2012). "Collectively, our current finding suggests that downregulation of EIF5A and HNRNPK by MS13 may inhibit cell proliferation and migration as well as induce apoptosis in glioblastoma and neuroblastoma cells." (PMID 33996900, 2021). "Moreover, EIF5A, DHPS, and DOHH are also highly expressed in glioblastoma (GBM), the most aggressive primary brain tumor in adults with a poor prognosis (a 5-year survival: ~5%)." (PMID 39125743, 2024). "Importantly, targeting eIF-5A and its hypusine modification with GC7, a specific DHS-inhibitor, showed a strong antiproliferative effect in glioblastoma cell lines in vitro, while normal human astrocytes were not affected." (PMID 22927971, 2012).
hepatocellular carcinoma (10 papers, 2011 to 2026). A malignant tumor that arises from hepatocytes. "Studies demonstrated over-expression of EIF5A enhances cell motility and promotes tumor metastasis in hepatocellular carcinoma." (PMID 23217164, 2012). "Overexpression of eIF5A has been found to induce hepatocellular carcinoma proliferation and skeletal stem cell differentiation." (PMID 21224998, 2011). "The overexpression of EIF5A induces the EMT, thereby promoting the tumor metastasis of colorectal and hepatocellular carcinoma." (PMID 23671674, 2013). "They showed, that an excess accumulation of the polyamine putrescine leads to a reduced formation of hypusinated eIF-5A and apoptosis in DH23A/b hepatoma cells." (PMID 22927971, 2012).
lung carcinoma (9 papers, 2012 to 2024). "A study revealed that the LLC cell-derived exosomes exhibited a high level of EIF5A, and an upregulation of EIF5A expression was linked to a reduction in the overall survival of patients with lung cancer." (PMID 38689293, 2024). "Eukaryotic translation initiation factor 5 A (EIF5A) is involved in the synthesis and degradation of DNA, RNA, and proteins, and its high expression was associated with poor prognosis in patients with lung cancer." (PMID 38689293, 2024). "EIF5A is also reportedly overexpressed in lung cancer, HCC, esophageal cancer and CRC, and it is associated with cancer cell aggressiveness and metastasis." (PMID 26214687, 2015). "In lung cancer, the increased expression of eIF5A protein is associated with the oncogenic mutations of K-ras at codons 12 and 13, which indicates that the K-Ras signaling pathway induces eIF5A expression." (PMID 34389018, 2021). "The lung cancer cell lines with higher DHPS protein levels showed higher hypusination levels of eIF5A and are more resistant to these inhibitors." (PMID 32989218, 2020). "IHC results also confirmed that GALNT3, CYCS, EIF5A, and ITGB4 were highly expressed in lung cancer tissues than normal lung tissues." (PMID 35651789, 2022).
lymphoma (7 papers, 2014 to 2025). A malignant (clonal) proliferation of B- lymphocytes or T- lymphocytes which involves the lymph nodes, bone marrow and/or extranodal sites. "In lymphoma, AMD1 acts as a tumor suppressor gene by regulating the posttranslational modification of eukaryotic translation initiation factor 5A (eIF5A)." (PMID 33413205, 2021). "Here, Scuoppo and co-workers demonstrated that the shRNA-mediated reduction of eIF5A expression, or decreased hypusine modification through knockdown of DHS, augmented lymphoma development in the Eμ-myc mouse model." (PMID 24832488, 2014).
malaria (7 papers, 2008 to 2022). Malaria is a serious and sometimes fatal disease caused by a parasite that commonly infects a certain type of mosquito which feeds on humans. "Since many examples showed a successful application of the replacement strategy in Plasmodium, we decided to investigate whether eIF‐5A and dhs genes might play an essential role in the proliferation of the parasite by loss of function in the rodent malaria parasite P. berghei." (PMID 27516964, 2016). "Hypusinated eIF‐5A controls the proliferation of cancer cells and inflammatory processes in malaria." (PMID 27516964, 2016). "However, only transgenic parasites with either eIF5A or dhs in their episome were obtained, suggesting a vital function in murine malaria blood stages." (PMID 35458660, 2022). "Therefore we addressed the question whether either DHS itself or eIF-5A is required for the outcome of severe malaria." (PMID 22694849, 2012). "Malaria parasites also possess canonical enzymes for hypusination of eIF5A, and the P. falciparum DHS enzyme (PfDHS) uses eIF5A protein as a substrate for incorporation of spermidine." (PMID 31024761, 2019). "Our data reveal significant and distinct isoform changes for several proteins (for example, eIF4A, eIF5A, and HSP70-2) as the malaria parasites progress through the late stage of their intra-erythrocytic life cycle." (PMID 19091060, 2008). "To our knowledge, we here describe the first experiments which demonstrate that a knock‐out of both eIF‐5A and dhs genes in Plasmodium by targeted gene disruption in the rodent malaria parasite P. berghei is not possible." (PMID 27516964, 2016).
developmental delay (6 papers, 2021 to 2024). "De novo heterozygous variants in EIF5A result in a disorder characterized by varying combinations of developmental delay, microcephaly, micrognathia and dysmorphism." (PMID 37930872, 2024). "Rare de novo heterozygous EIF5A variants were recently described in seven individuals (four females and three males, ages from 8 months to 18 years) with syndromic developmental delay and intellectual disability." (PMID 34273022, 2022). "The patients carrying biallelic DHPS variants, or heterozygous EIF5A variants, share common phenotypes including intellectual disability and developmental delay." (PMID 34688659, 2021). "Here, we demonstrate that de novo heterozygous EIF5A variants cause a previously undescribed syndrome characterised by variable combinations of developmental delay, microcephaly, micrognathia, congenital malformations and dysmorphism." (PMID 33547280, 2021). "We show that de novo heterozygous EIF5A variants cause a disorder characterized by variable combinations of developmental delay, microcephaly, micrognathia and dysmorphism." (PMID 33547280, 2021).
microcephaly (6 papers, 2021 to 2024). A congenital or acquired developmental disorder in which the circumference of the head is smaller than normal for the person's age and sex. "A rare, autosomal dominant disorder caused by heterozygous pathogenic EIF5A variants results in developmental delay, intellectual disability, microcephaly, and facial dysmorphism." (PMID 39334388, 2024). "A zebrafish model for eIF5A deficiency revealed mild microcephaly and micrognathia." (PMID 39334388, 2024). "Rare biallelic loss of function variants in DOHH were identified in an 8 year old girl presenting a severe neurodevelopmental disorder with several symptoms such as hypotonia, dysmorphic features, and microcephaly, overlapping with those found in DHPS and EIF5A-related disorders." (PMID 34273022, 2022).
colon carcinoma (5 papers, 2009 to 2024). "In addition, they found that simultaneous inhibition of ODC and eIF5A can downregulate MYC expression and decrease colon cancer cell growth." (PMID 37895010, 2023). "Moreover, the level of hypusinated EIF5A was also increased in the human colon cancer cell line HCT 116 and in a human organoid line derived from histologically normal colon tissue infected by EPEC; EIF5A level was not affected by EPEC infection in these cells." (PMID 39673545, 2024).
HIV-1 infection (5 papers, 2009 to 2023). The type species of lentivirus and the etiologic agent of acquired immunodeficiency syndrome (AIDS). "Given the dominant role of ODC-1-polyamine-EIF5A hypusination axis in promoting TregDys induction and proliferation during HIV-1 infection, we anticipated elevated levels of ODC-1 expression in TregDys." (PMID 36693889, 2023). "Of note, its conversion by DOHH into hypusyl-eIF5A remained unchanged after HIV-1 infection, as revealed by the identical amount of hypusine formed in infected untreated and uninfected untreated cultures." (PMID 27191165, 2016). "Iron and oxygen availability have been reported to affect HIV-1 infection in a number of studies, implicating several potential mechanisms including cell cycle effects mediated by factors such as eIF5A and CDK2." (PMID 24086341, 2013). "Further work will be required to define the function of mature eIF5A in HIV-1 infection and to establish the sequence of molecular events engendered by CPX and DEF." (PMID 19825182, 2009). "Our findings provide a mechanistic rationale to study such drugs for their ability to suppress HIV-1 infection in patients, and encourage the development of antiretroviral agents that target the posttranslational formation of hypusine in eIF5A." (PMID 19825182, 2009). "eIF5A is expressed in lymph nodes during acute HIV-1 infection, is overexpressed in lymphocytes of HIV-infected patients, and has been implicated as a cofactor for HIV-1 replication as well as a regulator of apoptosis triggered through the intrinsic mitochondrial pathway." (PMID 24086341, 2013). "Hypusine is essential for eIF5A function in HIV-1 infection and apoptosis." (PMID 24086341, 2013).
lung adenocarcinoma (5 papers, 2020 to 2025). A carcinoma that arises from the lung and is characterized by the presence of malignant glandular epithelial cells. "According to reports, eIF5A is highly expressed in a variety of tumors, and is associated with poor clinical features and prognosis, including lung adenocarcinoma." (PMID 34389018, 2021). "As high levels of eIF5A are a prognostic marker for poor lung adenocarcinoma patient outcome, we chose to study the effects of GC7 in A549 cells and observed a significant reduction in hypusination within 3 h." (PMID 41390489, 2025).
melanoma (5 papers, 2021 to 2026). A malignant, usually aggressive tumor composed of atypical, neoplastic melanocytes. "Based on this discovery, we designed specific RNA primers for RIP experiments (for details), and the results showed that METTL3 could bind to its mRNA in melanoma and eIF5A‐Hyp could also bind to the METTL3 mRNA." (PMID 38952061, 2024). "Here, we aimed to uncover the pro‐oncogenic mechanism of DHPS in melanoma by mediating the hypusination of eIF5A to promote the m6A modification of METTL3 itself through a multi‐omics approach to elucidate the value of DHPS as a therapeutic target for melanoma." (PMID 38952061, 2024). "In this study, we demonstrate in the BRAFV600E melanoma cells A375 and SK-MEL-28 that DHPS knockdown induces growth arrest associated with p21CIP1 upregulation whereas eIF5A knockdown induces cell death, and that p21CIP1 knockdown can switch the growth arrest induced by DHPS knockdown to cell death." (PMID 34947982, 2021). "EIF5A hypusination dependency of mitochondrial protein translation suggested that decreased mitochondrial biogenesis and function may be responsible for polyamine mediated BRAFi resistance in melanoma." (PMID 38965534, 2024). "Further works should assess the contribution of our newly identified mechanisms involving polyamine biosynthesis and EIF5A hypusination in the context of dynamic rewiring and adaptation of BRAF mutant melanoma upon BRAFi/MAPKi treatment." (PMID 38965534, 2024). "Taken together, these results suggest that DHPS mediates the hypusination of eIF5A by assisting METTL3 in recognizing its m6A site for methylation modification and maintaining the stability of mRNAs in melanoma cells." (PMID 38952061, 2024). "We investigated the mechanism underlying upregulation of polyamine biosynthesis in vemurafenib-resistant melanoma by first examining whether established vemurafenib resistance signaling, such as ERK or AKT, is responsible for increased EIF5A hypusination." (PMID 38965534, 2024). "The Co‐IP assays revealed that DHPS could not directly bind to METTL3 in melanoma cells, while eIF5A‐Hyp could bind to METTL3." (PMID 38952061, 2024). "Finally, we propose a paradigm shift: targeting the DHPS/eIF5A axis represents a strategy to disrupt the "non-oncogene addiction" of melanoma-its reliance on hyperactive translation and adaptive survival mechanisms-offering a promising avenue alongside targeted therapies and immunotherapies." (PMID 42072695, 2026). "Here we demonstrate that DHPS has a role independent of eIF5A hypusination in A375 and SK-MEL-28 human melanoma cells, in which the extracellular signal regulated kinase 1/2 (ERK1/2) pathway is deregulated." (PMID 34947982, 2021).
non-small cell lung carcinoma (5 papers, 2021 to 2023). A group of at least three distinct histological types of lung cancer, including non-small cell squamous cell carcinoma, adenocarcinoma, and large cell carcinoma. "MiR-4640-5p was found to interact with lncRNA OGFRP1 and regulate eIF5A expression in non-small cell lung cancer (NSCLC)." (PMID 36964568, 2023). "Previously, hsa-miR-4640-5p was shown to directly bind to the 3′-UTR region of eIF5A mRNA, inhibiting the expression of eIF5A in non-small cell lung cancer." (PMID 35002727, 2021).
pancreatic ductal adenocarcinoma (5 papers, 2020 to 2024). An infiltrating adenocarcinoma that arises from the epithelial cells of the pancreas. "SUMO2 conjugation to eIF5A is a stress-induced response implicated in the adaptation of yeast cells to heat-shock stress and required to promote the growth and migration of pancreatic ductal adenocarcinoma cells." (PMID 38229033, 2024). "eIF5A is upregulated in many different malignancies, such as pancreatic ductal adenocarcinoma, where a correlation between eIF5A levels and cancer progression and metastasis has been demonstrated." (PMID 38229033, 2024). "eIF5A is highly expressed in different types of cancer including pancreatic ductal adenocarcinoma (PDAC), in which its overexpression correlates with disease progression." (PMID 38229033, 2024). "Moreover, we show that the proproliferative and promigratory activities of eIF5A on pancreatic ductal adenocarcinoma cells require its SUMOylation." (PMID 38229033, 2024).
liver cancer (4 papers, 2016 to 2024). An epithelial or non-epithelial malignant neoplasm that arises from the liver. "Therefore, targeting eIF5A hypusination by inhibiting the glutamine-derived aspartate-mediated polyamine pathway is a promising therapeutic approach for liver cancer." (PMID 38689086, 2024).